RNU6-561P (RNA, U6 small nuclear 561, pseudogene)
Gene: Small nuclear RNA gene on chromosome 2 (79,636,862 to 79,636,963, reverse strand). Ensembl gene ENSG00000252031.
Homologues: Orthologues: chimpanzee U6 (98% identical), dog U6 (86% identical), rabbit RNU6-561P (82% identical), guinea pig U6 (62% identical). Paralogues in human: RNU6-393P (78% identical), RNU6-16P (77% identical), RNU6-1145P (76% identical), RNU6-836P (76% identical), RNU6-1067P (75% identical), RNU6-106P (75% identical), RNU6-10P (75% identical), RNU6-1124P (75% identical), RNU6-1152P (75% identical), RNU6-1251P (75% identical), RNU6-151P (75% identical), RNU6-29P (75% identical), and 1285 more.